METTL3 (methyltransferase 3, N6-adenosine-methyltransferase complex catalytic subunit)
Diseases named in the same sentence as METTL3 in open-access papers (continued):
Sharing a sentence is not in itself a finding about the gene and the disease.
tumor (continued). "Interestingly, a significant association between reduced METTL3 expression and advanced pathological stage was found, which is in accordance with the correlation between lower METTL3 expression and higher tumor grade observed by others." (PMID 35048498, 2022). "In NSCLC, METTL3-mediated Yes-associated protein (YAP) overexpression leads to tumor metastasis." (PMID 35331234, 2022). "Thus, all these results showed that METTL3 was associated with a variety of tumor-infiltrating immune cells, but its biological role in different immune cell subsets remains to be further explored." (PMID 36058919, 2022). "The COX model analysis showed that the expression of METTL3 and tumor diameter could be used as independent risk factors for prognostic prediction of the PC patients." (PMID 36058919, 2022). "Additionally, Mettl3- or Mettl14-deficient tumors upregulated cytotoxic tumor-infiltrating CD8+ T cells and increased the production of IFN-γ, Cxcl9 and Cxcl10 in the TIME of CRC in vivo, thereby enhancing the response to anti-PD-1 treatment." (PMID 36225914, 2022). "Supporting these results, another study demonstrated that METTL3 deletion in macrophages promotes tumorigenesis and metastasis by enhancing tumor-associated macrophages (TAMs) and T regulatory (Treg) cells infiltration into the tumor microenvironment (TME)." (PMID 36085064, 2022). "The reasons for the opposite conclusions reached for the same tumor and the same m6A protein may be due to sample problems, different transcripts of METTL3, or different risk factors that cause disease warrant further study." (PMID 35155557, 2022). "We further found that METTL3 deficiency inhibited CCA tumor growth in vivo." (PMID 36476503, 2022). "To investigate if METTL3 is required for NK cell-mediated anti-tumor immunity, we generated Mettl3fl/fl-Ncr1Cre/+ (cKO) mice, which harbored a selective deficiency of METTL3 expression at the mRNA or protein level in NK cells, with no change in METTL3 protein expression of T and B cells." (PMID 34535671, 2021). "Furthermore, the METTL3-mediated translation regulates hundreds of target mRNAs associated with tumour progression and apoptosis (e.g., EGFR, TAZ, MAPK2, DNMT3A, and BRD4)." (PMID 34638933, 2021). "Upon tumor challenge or IL-15 treatment, NK cell reduction was more profound in cKO mice, and IL-15-driven proliferation, survival, and activation were impaired in METTL3-deficient NK cells." (PMID 34535671, 2021). "Moreover, immunophenotyping of tumour tissues with METTL3-deficient macrophages through flow cytometry showed an increase in the overall percentage of M1- and M2-like TAMs." (PMID 33654093, 2021). "However, the loss-of-function analysis in larger cohort of tumor cell lines indicated the biological importance of METTL3 and METTL14 in cancer cell growth and survival." (PMID 34285249, 2021). "On the contrary, loss of METTL3 has also been shown to promote tumor growth and metastasis." (PMID 34616742, 2021). "The expression of METTL3, an m6A writer gene, was higher in the high-risk group and tumor samples, which has been reported to regulate the cell cycle, cancer stem cells, and metabolism, resulting in tumor cell proliferation, metastasis, and tumorigenesis." (PMID 34512654, 2021). "Abnormal regulation of METTL3 is associated with many aspects of tumor development." (PMID 34794452, 2021). "RNA-seq analysis under METTL3 knockdown revealed DEGs involved in the cell cycle, apoptosis process, immune response, cell adhesion, and defense response, supporting the tumor-promoting effect of METTL3, and reflected that the transcription regulation underlies the tumor-promotor role METTL3." (PMID 35117988, 2021). "To explore whether the loss of Mettl3 in BMDMs enhances tumour growth, we established a mixed model of macrophages and tumour cells." (PMID 33654093, 2021).
tumor (continued). "We next quested whether the loss of Mettl3 was able to inhibit the expression of specific targets involved in tumor angiogenesis such as TEK and VEGF-A." (PMID 33681207, 2021). "Furthermore, the therapeutic efficacy of PD-1 checkpoint blockade is attenuated in Mettl3-deficient mice, identifying METTL3 as a potential therapeutic target for tumour immunotherapy." (PMID 33654093, 2021). "The METTL3–METTL14 complex mediates expression of tumor-related genes via m6A modification of associated mRNA, thus controlling cancer stem cell pluripotency, tumor initiation, epithelial-mesenchymal transformation (EMT), angiogenesis, and the DNA-damage response." (PMID 32296573, 2020). "Recent studies have shown that METTL3 is closely associated with the processes involved in the progression of gastrointestinal cancer, including tumor proliferation, apoptosis, metastasis, angiogenesis, chemo/radiotherapy resistance, glycolipid metabolism, and cancer stem cell (CSC) maintenance." (PMID 32429972, 2020). "Then, the researchers also found that low level of METTL3 was associated with larger tumor size and higher histological grade in vivo study, and could promote RCC cell proliferation, migration and invasion function and induced G0/G1 arrest in vitro study." (PMID 32038982, 2020). "However, little attention has been paid to the role of METTL3 in the crosstalk between cancer cells and tumor-associated fibroblasts and immune cells in the tumor microenvironment." (PMID 32429972, 2020). "The results indicate that METTL3 could directly induce CD33+CD11b + HLA-DR− MDSC differentiation or tumour-associated MDSC differentiation in vitro." (PMID 33059689, 2020). "Further investigation showed the underlying mechanism whereby HBXIP inhibited the tumour suppressor let‐7 g, which could down‐regulate METTL3." (PMID 30039919, 2018). "Pan-cancer analyses indicate that METTL3 expression correlates with immune cell infiltration, tumor mutation burden, microsatellite instability, mismatch repair gene expression, and epithelial-mesenchymal transition, underscoring its broad impact on both tumor progression and immune modulation." (PMID 41322419, 2025). "Recent literature has indicated that m6A methylation of mRNA induced by METTL3 may cause various mammalian diseases and tumours by modulating tissue development and cell differentiation and is a cause of tumorigenesis and tumour progression in different cancers." (PMID 39095708, 2024). "In addition, the inhibition of PD-1 checkpoints results in a diminished therapeutic effect in METTL3-deficient mice, indicating that METTL3 could serve as a potential target for tumor immunotherapy." (PMID 39759516, 2024). "In addition, METTL3 has been reported to be involved in the differentiation and development of normal myeloid cells 38 and may be involved in the induction of tumor-related MDSCs 39; still, the underlying mechanism is unknown." (PMID 37649603, 2023). "In addition, METTL3 regulates the infiltration of tumor-associated neutrophils." (PMID 37671161, 2023). "Moreover, silencing METTL3 could suppress tumor proliferation and migration and was also associated with lymphoid enhancer-binding factor 1 (LEF1) and Wnt/β-catenin signaling pathway." (PMID 35860263, 2022). "We discovered that METTL3 is primarily implicated in chromosomal homologous recombination and DNA mismatch repair, which could be potential mechanisms for the occurrence and progression of tumor diseases." (PMID 35574315, 2022). "In addition, decreased METTL3 expression in bone marrow cells can promote tumor growth and metastasis in vivo, and the infiltration of M1 and M2 tumor-associated macrophages and regulatory T cells was increased significantly in tumor tissues in METTL3-deficient mice." (PMID 35965524, 2022). "Since METTL3 is highly expressed in GC and is associated with poor prognosis of patients with GC, an assumption was made that METTL3 could perform the function of tumor promoter in GC." (PMID 35742899, 2022).
tumor (continued). "In addition, the deficiency of MettL3 or Mettl14 in tumors results in enhancing cytotoxic tumor-infiltrating CD8+ T cells, and increasing the secretion of IFN-c, Cxcl9 and Cxcl10 in TME in vivo, which proves that the immune system and tumor microenvironment have metastasized in tumor m6A mRNA." (PMID 35069586, 2021). "More importantly, this study proposes that targeting Mettl3 might bring profound influence on conquering chemotherapy resistance and immunotherapy tolerance caused by tumor angiogenesis, offering therapeutic alternatives to patients suffering this treatment dilemma." (PMID 33681207, 2021). "Therefore, we wondered whether METTL3 expression may be linked to the density of tumour-infiltrated MDSCs." (PMID 33059689, 2020). "Importantly, we demonstrated that knockdown of METTL3 in CD33+ cells or HeLa cells could attenuate MDSC or tumour-associated MDSC differentiation in vitro." (PMID 33059689, 2020). "We next examined whether disruption of METTL3 is associated with tumor progression." (PMID 31363082, 2019). "Increasing evidence suggests that dysfunction of PUS family members, similar to mutations in m6A methyltransferases such as METTL3 and METTL14, is closely associated with tumour initiation, progression, and immune evasion." (PMID 41496500, 2026). "Its inhibition of METTL3 triggers the upregulation of innate immune genes, spurring an anti-tumor response that curbs cancer cell proliferation." (PMID 41522342, 2026). "Future studies should aim to clarify the upstream regulatory networks governing Mettl3, define its context-dependent tumor-suppressive effects, and advance the development of targeted pharmacological inhibitors." (PMID 41517663, 2026). "Phosphorylation enhances METTL3's catalytic function and promotes tumor cell proliferation, while SUMOylation regulates nuclear retention and stability." (PMID 41457744, 2026). "CRCs display variable sensitivity to METTL3 inhibition: tumours with high basal dsRNA and RNA methylation respond to METTL3 blockade alone, whereas those with low RNA methylation require combination therapy." (PMID 42135281, 2026). "METTL3 levels were markedly elevated across 14 tumor types, including lung adenocarcinoma (LUAD) and lung squamous cell carcinoma (LUSC)." (PMID 41362669, 2026). "In vivo, METTL3 knockdown significantly attenuated subcutaneous tumor growth in nude mice (p < 0.05) and reduced PD-L1 and CD163 expression (p < 0.05)." (PMID 42064710, 2026). "Mettl3 knockdown partially inhibits the invasive tumor phenotype PDAC by reducing m6A modification of DDX23 mRNA." (PMID 41517663, 2026). "Our result revealed that the ablation of METTL3 significantly inhibited tumor formation and reduced the tumor weight (n = 7; p < 0.05), consistent with the results demonstrating that METTL3 knockout inhibited the cell proliferation of ESCC cells in vitro." (PMID 41262526, 2026). "Conducting a detailed comparison of METTL16 with the canonical METTL3–METTL14 complex is critically important for uncovering the distinctive functions that METTL16 exerts in tumor initiation and progression." (PMID 41459114, 2026). "methyltransferase-like 3 (METTL3)-mediated N6-methyladenosine (m6A) RNA methylation plays a crucial role in tumor initiation and progression by regulating RNA function." (PMID 41875089, 2026). "Inhibition of METTL3 remodels the tumor microenvironment and enhances the efficacy of programmed cell death protein-1/PD-L1 blockade therapy." (PMID 41200062, 2026). "Mechanistically, METTL3 deficiency reduced m6A modification and expression of bone morphogenetic protein 10 (BMP10), a known tumor suppressor." (PMID 42030359, 2026). "The expression level of METTL3 is abnormally increased in a variety of tumor types, such as lung, liver, breast, gastric, colorectal and pancreatic cancer, and is closely related to the occurrence, development and prognosis of tumors." (PMID 40678060, 2025).
tumor (continued). "IHC analysis of ~2500 BCa tumour specimens revealed an association of increased METTL14 and CBLL1 with favourable clinical outcomes in BCa and increased METTL3 expression with poor clinical outcomes in hormone receptor negative BCa." (PMID 41310336, 2025). "In tumor-infiltrating myeloid cells (TIMs), METTL3-mediated m6A modification of Jak1 mRNA enhances JAK1 protein translation efficiency through the m6A-YTHDF1 axis, leading to increased phosphorylation of STAT3." (PMID 40244180, 2025). "Why are METTL3/METTL14 suppressed during the lytic phase but highly expressed during the tumor phase?" (PMID 40778336, 2025). "Our results demonstrated that silencing METTL3 significantly impeded tumor growth, leading to a notable reduction in tumor volumes and weights." (PMID 39472692, 2025). "Arsenic exposure specifically downregulates METTL3, which reduces m6A methylation in tumor-suppressor RNAs, hence degrading them and fostering oncogenesis." (PMID 40760453, 2025). "Dysregulation of these writers reshapes the tumor microenvironment (TME): for example, METTL3 overexpression in tumor cells promotes myeloid-derived suppressor cell (MDSC) accumulation via the BHLHE41–CXCL1/CXCR2 axis, dampening CD8+ T-cell responses." (PMID 41280938, 2025). "METTL3 is essential for epithelial‒mesenchymal transformation (EMT) in tumor cells in vitro and for metastasis in vivo." (PMID 41312360, 2025). "METTL3 also promotes tumor angiogenesis by modifying Ephrin-A receptor 2(EphA2) and vascular endothelial growth factor A (VEGFA) mRNAs with m6A, facilitating their recognition by IGF2BP2/3, stabilizing the mRNA, and enhancing protein translation." (PMID 39791162, 2025). "METTL3 acts as an m6A methyltransferase and functions as both an oncogenic regulator and a tumor suppressor in diverse cancers." (PMID 40510136, 2025). "CAFs can transfer METTL3 to tumor cells via secreted factors and exosomes, elevating intracellular m6A levels and altering gene expression profiles such as SLC7A5 to support tumor growth." (PMID 40740874, 2025). "For instance, inhibition of FTO or METTL3 has shown promise in preclinical models by disrupting DNA repair efficiency and promoting tumor cell death." (PMID 40760453, 2025). "In HBV-related HCC, the METTL3-mediated upregulation of lncRNA MAAS in M2 macrophages drives tumor progression." (PMID 40034695, 2025). "METTL3 lactylation creates a lactylation-m6A-JAK1-STAT3 axis in CRC, causing immunosuppression and promoting tumor progression." (PMID 40994548, 2025). "Methyltransferase‐like 3 (METTL3), an integral component of the m6A “writer” methyltransferase complex, is upregulated in PCa, and its increased expression promotes tumor growth, correlating with advanced tumor staging and poor prognosis." (PMID 39948708, 2025). "Compared to normal bladder tissues, METTL3 is highly expressed in BCa tissues and regulates multiple tumor characteristics, including cell proliferation, metastasis, anti-apoptosis, and chemoresistance." (PMID 40678060, 2025). "TRIM21-mediated METTL3 ubiquitination as a critical regulator of ferroptosis to prevent tumor progression." (PMID 40175350, 2025). "As an essential component of the m6A methyltransferase complex, METTL14 cooperates with METTL3 and also significantly contributes to tumor progression in various cancer types." (PMID 40640957, 2025). "Conversely, it was discovered that the number of CD8+ T cells, a kind of antitumor T cell, infiltrated a tumor was inversely correlated with the number of METTL3 mRNA copies (all p < 0.001, cor < 0)." (PMID 40177651, 2025). "In the context of m6A modification, elevated levels of METTL3 expression correlate with unfavorable prognosis, increased tumor malignancy, and reduced overall survival (OS)." (PMID 41584846, 2025).
tumor (continued). "In light of these discussions, future research should prioritise elucidating the precise mechanisms by which METTL3 contributes to the tumour microenvironment in OS." (PMID 40052548, 2025). "The acidic tumor microenvironment suppresses T‐cell recruitment and impairs anti‐tumor immunity by downregulating the METTL3‐m6A‐integrin β1 signaling pathway." (PMID 41316520, 2025). "Specifically, the abnormally upregulated METTL3 commonly promotes tumour proliferation, migration, and invasion while suppressing apoptosis, indicating a strong correlation of METTL3 with poor prognosis." (PMID 40052548, 2025). "METTL3-m6A-EGFR-axis was responsible for acquired resistant to lenvatinib, and the particular METTL3 inhibitor STM2457 amplified tumor response to lenvatinib in HCC animal models via increasing cell apoptosis." (PMID 40083703, 2025). "This review synthesizes METTL3's roles in BC progression, including tumor initiation, metastasis, stemness, and therapy resistance." (PMID 40778544, 2025). "In CRC, lactate induces H3K18 lactylation in tumor-infiltrating macrophages, leading to the upregulation of METTL3." (PMID 40994548, 2025). "m6A, driven by METTL3, modulates key oncogenic and tumor-suppressor pathways, while m5C, mediated by NSUN2, supports codon-dependent translation for cancer progression." (PMID 40463874, 2025). "The zinc finger protein ZNF677, a zinc finger protein family member, a tumor suppressor in ccRCC, is epigenetically regulated by METTL3." (PMID 40313614, 2025). "TRIM21 overexpression significantly suppressed tumor growth in mouse xenograft model, which was completely rescued by the restored expression of METTL3." (PMID 40175350, 2025). "Research has shown that METTL3 promotes tumor progression by stabilizing oncogenes, enhancing chemoresistance, and regulating the tumor immune microenvironment." (PMID 40678060, 2025). "Mechanistically, the downregulation of METTL3-mediated m6A modification on ARHGEF12 mRNA accelerated its degradation, a process that is closely associated with tumor behaviors." (PMID 40332203, 2025). "For example, the m6A writer METTL3 enhances anti-tumor immunity by promoting infiltration of CD8+ T cells and NK cells, effectively reversing extrinsic immunosuppressive conditions." (PMID 41050070, 2025). "In the context of CTCL, current research suggests a tumor-suppressive role for METTL3 by modulating CDKN2A expression." (PMID 40332203, 2025). "The immunosuppressive function of tumor‐infiltrating myeloid cells (TIMs) influences both tumor cell survival and the process of programmed cell death, primarily through METTL3 regulation." (PMID 39802639, 2025). "Its expression level is significantly higher in advanced GC compared to early-stage cancer, and combining METTL3 expression with tumor, node, and metastasis (TNM) staging improves the accuracy of prognostic assessment." (PMID 41446042, 2025). "Decreased RNA m6A methylation promotes EMT and vasculogenic mimicry processes in GBM, with ALKBH5 upregulation or METTL3 downregulation driving increased tumor invasiveness." (PMID 40565099, 2025). "Its role in cancer progression is context-dependent, with methyltransferase-like protein 3 (METTL3), a core methyltransferase, exerting both oncogenic and tumor-suppressive effects in cancers." (PMID 40463874, 2025). "The METTL3-specific inhibitor STM2457 has demonstrated preclinical efficacy not only in directly suppressing tumor growth but also in modulating the tumor immune microenvironment." (PMID 41312360, 2025). "Histological analysis also showed that Mettl3 cKO mice exhibited more tumor‐like nodules and cells with abnormal nuclear morphology." (PMID 40103332, 2025). "METTL3 expression was significantly increased in tumor tissues when compared with the normal tissues." (PMID 39980152, 2025). "This increased expression of METTL3 enhances the translation of specific oncogene mRNAs via M6A modification, subsequently promoting the proliferation and survival of tumor cells." (PMID 41312360, 2025).